VIM (vimentin)
Diseases named in the same sentence as VIM in open-access papers (continued):
Sharing a sentence is not in itself a finding about the gene and the disease.
tumor (continued). "During EMT, tumor cells acquired highly aggressive capabilities and lost expression of epithelial markers, such as E-cadherin, and increased expression levels of mesenchymal markers, such as N-cadherin, Snail, and Vimentin." (PMID 35211171, 2022). "Vimentin upregulation at the control tumor periphery and untreated tumor in scant histotripsy on day 7, may be linked to metastatic invasion." (PMID 35406383, 2022). "In addition, a reduction in the proliferation and invasion signature genes (ki67,vimentin) were observed in tumour with downregulated LMO1." (PMID 35280742, 2022). "TNF-α can induce EMT in tumor cells by inhibiting the expression of epithelial marker E-cadherin, upregulating the expression of mesenchymal markers such as vimentin, N-cadherin, and fibronectin, and activating matrix metalloproteinase-9 (MMP-9), thus enhancing tumor invasion and migration activity." (PMID 35965509, 2022). "Direct platelet–tumor cell interaction was associated with enhanced mRNA expression of COX-2 (but not COX-2 protein), epithelial–mesenchymal transition (EMT)-inducing transcription factors, such as ZEB1 and TWIST1, and the mesenchymal marker vimentin (VIM)." (PMID 35203374, 2022). "Likewise, EMT event, which is chiefly marked by the decrease of E-cadherin and the increase of vimentin, occupies an important position in tumor metastasis." (PMID 35333683, 2022). "Thus, human vimentin reliably identifies all human tumor cells in the studied section of affected organs, including single EC cells infiltrating the tissue (which anti-CXCR4 or H&E cannot) and small or large size metastatic foci." (PMID 35884987, 2022). "To test whether the TMEM116 positive cells underwent epithelial-mesenchymal transition (EMT) in tumor tissues, we conducted immunostaining with antibody against Vimentin and N-Cadherin." (PMID 34789718, 2021). "Moreover, PcrV treatment did not affect the expression levels of genes (e.g., Cox2, Mmp9, Vegfa, and Hif1a) or proteins (e.g., COX2 and vimentin) related to tumor growth and metastasis, or the metastatic ability of LLC cells." (PMID 34900687, 2021). "Furthermore, we confirmed the expression of vimentin because it is overexpressed in most epithelial cancer and correlates with tumor growth and poor prognosis." (PMID 33498448, 2021). "We could show that WF significantly increased the expression of Snail 2 and vimentin in both tumor cell lines." (PMID 33922946, 2021). "Meanwhile, miR-199b-5p restoration or DDR1 silencing can induce a transition from a mesenchymal-like toward a more cobblestone-like epithelial phenotype, as supported by the E-cadherin overexpression and the downregulation of vimentin and fibronectin expression in PCa cells and xenograft tumours." (PMID 33239676, 2021). "Furthermore, Vimentin and β-catenin exhibited elevated expression levels in peritoneal metastasis than primary tumor tissues." (PMID 35003354, 2021). "Numerous GFAP/vimentin double-positive cells aligned at the tumor border (PT)." (PMID 34441246, 2021). "In addition, the expression of Vimentin was up‐regulated, whereas the expression of E‐cadherin was down‐regulated in tumours infected with Lv‐shHDAC2 as detected by IHC." (PMID 33325150, 2021). "VIM expression during cancer development has been found to correlate with tumor growth, and the increased presence of surface VIM on tumor endothelial cells may indicate a role of this protein in tumor metastasis and/or invasion." (PMID 34571970, 2021). "Furthermore, vimentin silencing in these cells also impairs xenografted tumor growth on chick embryo chorioallantoic membranes, indicating a role of vimentin in cell growth." (PMID 34203746, 2021). "Similarly, Li and Xu showed that propranolol blocked the effect of fear stress on tumor growth in PC xenograft animal models by decreasing Frizzled-1 (Fz1), Wnt-1 and vimentin protein expression." (PMID 34439102, 2021). "The tumor tissues of these patients showed high vimentin and lost E-cadherin protein expression." (PMID 33789624, 2021).
tumor (continued). "Moreover, Asahina and others suggested that the lesion derived from the intercalated duct cell due to the presence of the tumour cells coexpressing cytokeratin, vimentin, and desmin." (PMID 33712056, 2021). "Both sets of results suggested that elevated miR-30b/-30d enhanced the protein expression of E-cadherin, while reducing that of SEMA6B, N-cadherin, and vimentin in subcutaneous xenotransplanted tumor tissues, which was abrogated by the overexpression of SEMA6B." (PMID 33738326, 2021). "Ancel and colleagues reported that a cut-off ≥ 25% vimentin-positive tumor cells was significantly associated with poor tumor differentiation even if it was not sufficient to predict a worse prognosis." (PMID 34917615, 2021). "Furthermore, the three cell components of the tumor in the present case showed different expression patterns of β-catenin, E-cadherin, and vimentin, suggesting heterogeneous WNT pathway alterations in the tumor cells." (PMID 34513702, 2021). "Therefore, the combination of calponin and vimentin is recommended for the identification of myoepithelial cells in neoplasms, as these cells can be found in various stages of differentiation." (PMID 33809250, 2021). "Furthermore, SP1 participated in tumor progression via regulating multiple downstream genes, such as vimentin, cadherin, E-cadherin, and CDK2." (PMID 33345272, 2021). "In addition, with the analysis of histological and IHC in tumor sections, the expression levels of Ki67 and vimentin were higher, while the E-cadherin expression level was lower in the sh-LINC00342 group than the sh-NC group (P < 0.01)." (PMID 33588834, 2021). "However, more detailed information regarding the binding of F7 and SP peptides to nucleolin and vimentin respectively is required for the potential application of these tumor targeting peptides in detection and isolation approaches." (PMID 34789743, 2021). "In addition, higher levels of Vimentin were consistently seen in tumor tissues derived from knockdown control MT-LE cells compared with knockdown control parental cells, which were dramatically suppressed in xenograft tumors when FGF19 was depleted." (PMID 33691750, 2021). "Furthermore, PRL1 overexpression increased the levels of N-cadherin and Vimentin, and decreased that of E-cadherin in the tumor sections." (PMID 35111679, 2021). "Thus, we determined the expression level of N-cadherin and vimentin, which are prognostic markers of tumor progression." (PMID 34108938, 2021). "However tumor cells were revealed positivity for vimentin, soluble protein-100, and alpha-thalassemia/mental retardation syndrome X, GFAP strong positive in the cytoplasm." (PMID 34713831, 2021). "Although immunohistochemistry lacksspecificity, the tumor may express vimentin and smooth muscle actin." (PMID 34077396, 2021). "Importantly, the expression of vimentin in different tumor cell lines is closely related to cancer cell growth, invasion and migration." (PMID 34830378, 2021). "Furthermore, IHC staining of CFL1, EMT markers (E‐cadherin, N‐cadherin, and Vimentin) was performed in subcutaneous tumour tissues and lung metastases." (PMID 33784016, 2021). "Future studies have to reveal whether vimentin+ cells also derive from tumor cells having undergone epithelial-to-mesenchymal transition (EMT)." (PMID 34290694, 2021). "EMT is widespread in malignant tumor cells, of which VIM is a marker gene." (PMID 34745226, 2021). "In addition, vimentin expression in 5 – 10% tumor cells suggests that possibly these cells have been transformed to mesenchymal cell type." (PMID 34778599, 2021).
tumor (continued). "Immunohistochemically, the tumor cells were positive for vimentin, smooth muscle actin (SMA), CD34, and endothelial membrane antigen (EMA) and negative for desmin, erythroblast transformation-specific related gene (ERG), myoglobin, S-100 protein, HMB-45, melan-A, CD117, AE1/AE3, and CAM5.2." (PMID 34193249, 2021). "We also noticed although the expression of vimentin was low in GPNMB low expression tumor part, the expression of vimentin was high in its stroma compartment, which may act as a measure of internal quality control in IHC44,45." (PMID 34108545, 2021). "β-catenin plays an important role in the regulation of many tumor-related events and its activation may result in upregulation of vimentin expression." (PMID 33803107, 2021). "Moreover, EMT markers (E-cadherin, N-cadherin and vimentin) were reported to be correlated with tumor progression in NSCLC." (PMID 33858512, 2021). "Furthermore, both GPC3 and FAT1 regulated the expression of tumor metastasis-related genes, e.g., Snail, Vimentin, and E-Cadherin." (PMID 33420124, 2021). "Furthermore, we found that overexpression of BRCA1 in these cells induced expression of CDH1 (encoding E-cadherin) while inhibiting expression of FOSL1 (encoding FRA1) and VIM, consistent with our finding that deficiency of Brca1 induced EMT in tumor cells." (PMID 33478572, 2021). "In 90% of the tumor, IHC studies revealed positive vimentin, CK7, PAS, and CA19-9." (PMID 34150416, 2021). "Moreover, tumor biopsy samples from EGFR-TKI resistance patients presented increased vimentin expression and downregulated E-cadherin expression compared with tumor tissues taken before TKI treatment." (PMID 33170304, 2021). "Hence, we continued to explore the tumor-suppressive mechanisms of HRD1 targeting Vimentin degradation." (PMID 33530981, 2021). "Besides, the expression of N‐cadherin and Vimentin, which are important regulatory biomarkers of tumor aggressiveness, significantly reduced upon MTFD2 depletion." (PMID 34231329, 2021). "In addition, the NanoVelcro CTC Assay identified a vimentin-positive subpopulation of CTCs that indicated a particularly aggressive biological tumor behavior." (PMID 34884878, 2021). "Immunohistochemically, tumor cells were positive for cytokeratin and vimentin." (PMID 33950950, 2021). "Furthermore, IHC staining revealed that intratumoral injection of overexpressed circESRP1 enhanced the E-cadherin expression, but decreased the levels of PCNA, c-Myc, and Vimentin, indicative of lower aggressive capabilities of tumor growth and metastasis." (PMID 34775467, 2021). "Tumor was positive for vimentin and melan-A and inhibin-α was moderate in occasional tumor cells." (PMID 34803919, 2021). "ERRα can play the role of tumor promoter, and it can promote cell migration and invasion by increasing the levels of E-cadherin and γ-catenin and decreasing the levels of N-cadherin and vimentin." (PMID 33591949, 2021). "In this patient, tumor cells were reactive for vimentin and alpha-SMA." (PMID 34797454, 2021). "The expression of CD133 and Vimentin were detected in 50% and 58% of tumor samples, respectively." (PMID 34771484, 2021). "Additionally, the number of vimentin positive cells was ≥50% in each xenograft tissue, thus demonstrating a similar level of tumour differentiation." (PMID 34768368, 2021). "In the primary tumor, BCCs lose epithelial proteins such as lectin and cytokeratin and gain mesenchymal proteins such as vimentin and neuronal (N)-cadherin, a process known as epithelial–mesenchymal transition (EMT), which endows cells with invasive and migratory properties." (PMID 33671551, 2021). "Additionally, the stromal cell-specific intermediate filament vimentin is characterized by oncogene properties, promoting faster tumour growth, cell migration, and invasion." (PMID 34204745, 2021). "Therefore, VIMENTIN is a potential molecular target that can be inhibited to struggle with tumor cells invasion and localization at other tissues." (PMID 35178358, 2021).
tumor (continued). "In this sample, vimentin expression was observed in the stroma of the primary tumor." (PMID 34198671, 2021). "IHC staining results indicated that the knockdown of ANXA2P2 observably promoted E-cadherin protein expression, while inhibiting N-cadherin and Vimentin expression, while miR-361-3p knockdown exerted opposite effects on the tumor metastasis protein expressions." (PMID 35083143, 2021). "Considering the higher abundance of circulating tumor cells (CTCs) in portal vein blood compared to in peripheral blood, researchers have discovered that the count of mesenchymal-CTCs and vimentin+ CTCs correlates with a poorer differentiated tumor and a shorter survival." (PMID 34771461, 2021). "On the other hand, high Vimentin tumor expression has a trend to a poor PFS (p = 0.056)." (PMID 34771484, 2021). "Recent evidence has revealed that TIPE2 could suppress the migration of tumor cells by promoting the induction of E-cadherin expression and inhibition of N-cadherin and vimentin expression." (PMID 34630074, 2021). "Thus, cytoskeleton remodeling maintained the balance of cell anchoring and detachment, and the TGF-β1/vimentin/focal adhesion protein assembly axis was involved in the control dynamics of initial tumor detachment." (PMID 34830801, 2021). "Moreover, LINC-ROR silencing results in the inhibition of cell proliferation, invasion, and EMT through reducing CDH1 expression and increasing the expression of ZEB1/2 and Vimentin in ESCC tumor tissues." (PMID 33745265, 2021). "An important novel aspect of the present study is that the associations between DCE-MRI derived parameters with vimentin and tumor-stroma ratio differ significantly between HPV negative and positive HNSCC." (PMID 34801089, 2021). "Also VIMENTIN expression level in bone marrow is clearly related with tumor invasion and lymph node metastasis ability of GC cells." (PMID 35178358, 2021). "IHC staining on tumour sections of metastasized lungs demonstrated that upregulation of Tspan5 significantly reduced the expression of E‐cadherin but increased the expression of vimentin in MHCC97L and BEL7402 tumours." (PMID 33955149, 2021). "Tumor cells were positive for Melan A, Calretinin and Vimentin suggesting an adrenal origin." (PMID 34307221, 2021). "An inhibition of SLUG and an elevated VIM expression were observed in this tumor model." (PMID 33368325, 2021). "Tumor metastasis is significantly associated with EMT, a process that involves cancer cells acquiring mesenchymal characteristics (expression of N-cadherin and vimentin) and losing epithelial features (expression of E-cadherin)." (PMID 34096887, 2021). "Eventually, tumor cells lose their capacity to interact with one another and gain increased migratory capacity due to increased expression of mesenchymal proteins, such as vimentin and a-SMA." (PMID 33591949, 2021). "To further validate the TdIF1-LSD1 interaction and to explore the potential additive and/or synergistic suppressive effect of tumor cell invasion by simultaneously repressing both molecules, we measured the expression of E-cadherin, N-cadherin, and vimentin using Western blot analysis." (PMID 35008676, 2021). "Interestingly, no change in expression levels of mesenchymal-associated genes VIM, EGFR, FOSL1 and FN1 was observed between CTCs and their primary tumours in any of the models." (PMID 34206049, 2021). "Tumor cells showed characteristic paranuclear dot-like positive signals for desmin and vimentin." (PMID 34193155, 2021). "Vimentin staining shows the presence of CAFs even after tumor shrinkage with APX2009 treatment." (PMID 34376225, 2021).
tumor (continued). "In epithelium-derived cancers, intracellular vimentin has long been known to be involved in the process known as epithelial-to-mesenchymal transition, which describes a particular moment during the progression of tumor cells to metastases." (PMID 34299089, 2021). "Our study showed that Co(II)-containing compounds target vimentin in Hep G2 tumour cells." (PMID 33670389, 2021). "Tumor specimens were immunohistochemically stained for vimentin and E-cadherin." (PMID 33789624, 2021). "Vimentin is abundantly expressed in several aggressive cancer cell lines, and broadly reported to play a critical role in acquisition of the migratory and invasive tumor cell phenotype during the epithelial-mesenchymal transition." (PMID 33530981, 2021). "In conclusion, we elucidated a novel tumor-suppressive role of HRD1 via inducing polyubiquitination-mediated proteasomal degradation of Vimentin, which could be upregulated by circNR3C2 through sponging miR-513a-3p." (PMID 33530981, 2021). "We found that circ_0008594 overexpression increased tumor volume, Vimentin expression, and Snail expression, while reduced tumor apoptosis rate, miR-760 expression, and E-cadherin expression in NSCLC xenograft models; moreover, circ_0008594 knockdown exhibited the opposite effect." (PMID 34858831, 2021). "The vimentin are highly expressed in a variety of tumor cells, especially in tumor cells with EMT." (PMID 34168982, 2021). "These analyses revealed that the tumors lacked expression of any markers of muscle differentiation (PAX7, MYOD, MYOGENIN) but were positive for VIMENTIN, while some spindled and larger eosinophilic tumor cells expressed smooth muscle actin (SMA), suggestive of focal myofibroblastic differentiation." (PMID 33924486, 2021). "In addition, increased expression levels of N‐cadherin and vimentin are also critical markers of the EMT process during tumour progression." (PMID 34636136, 2021). "On the other hand, EpCAM could be lost during the epithelial to mesenchymal transition (EMT) process, as tumor undifferentiation leads epithelial cell lines to recover stem-cells’ characteristics, including the expression of other markers such as vimentin." (PMID 34069569, 2021). "Furthermore, we detected the expression of E-cadherin and Vimentin in primary tumor tissues from orthotopic xenograft model mice." (PMID 33808696, 2021). "In addition, the miR-146a expression in TCGA tumor samples was negatively correlated with the E-cadherin to Vimentin ratio." (PMID 34712602, 2021). "Vimentin, a mesenchymal marker, can play fundamental roles in tumor invasion and metastasis." (PMID 33789624, 2021). "There is no doubt that the detection and analysis of CTC markers (EpCAM and CK8, 18, CD45 Vimentin, Twist and 19) and CSCs markers (Nanog) are useful for evaluating tumor progression, developing tumor drugs, and monitoring the disease process of cancer patients." (PMID 34123777, 2021). "Moreover, western blot results demonstrated an increased protein expression of E-cadherin and a decreased protein expression of Vimentin within tumours from GD-treated mice." (PMID 32958824, 2020). "Vimentin is a mesenchymal marker often recorded in tumor cell invasions and correlated with EMT." (PMID 32790767, 2020). "Similarly, overexpression of vimentin in ESCC cells is correlated with increased tumor growth, invasion, poor prognosis, and lymph node metastasis." (PMID 33248456, 2020). "Compared with the GBM mono-culture, reactive astrocytes promoted the upregulation of GFAP and vimentin proteins in the tumor microenvironment and possibly formed a functional barrier called a glial scar, thus increasing GBM chemoresistance, that needs to be further investigated." (PMID 32998285, 2020). "Indeed, our results showed that tumor AUB-PrC cells demonstrate some vimentin (mesenchymal cell marker) expression as well which further validate our point." (PMID 33195205, 2020).